SRSF6 (serine and arginine rich splicing factor 6)
Diseases named in the same sentence as SRSF6 in open-access papers (continued):
Sharing a sentence is not in itself a finding about the gene and the disease.
cancer (34 papers, 2009 to 2025). A tumor composed of atypical neoplastic, often pleomorphic cells that invade other tissues. "Perhaps dysregulation of the immune milieu is part of why SRSF6 upregulation is associated with poor cancer outcomes." (PMID 36409059, 2022). "SRSF6 mutation frequencies in cancers are relatively lower (<5%) compared with those in SRSF2 [10–50% in hematologic malignancies]." (PMID 34917618, 2021). "In summary, alternative splicing regulator SRSF6 is overexpressed in many types of cancer and associated with poor prognosis in some cancers." (PMID 34917618, 2021). "We summarized SRSF6 mutations in different types of cancer according to cBioPortal online TCGA cancer database." (PMID 34917618, 2021). "More pieces of evidence are required to determine the association between SRSF6 expression and cancer patient prognoses." (PMID 34917618, 2021). "SRSF6 behaves as an oncogene protein and is associated with proliferation, transformation, and tumorigenicity of immortal cancer cells." (PMID 32793473, 2020). "Further studies are required to understand the roles of SRSF6 mutations in cancer." (PMID 34917618, 2021). "SRSF6 is associated with the progression of various cancers." (PMID 33622363, 2021). "Mutations of SRSF6 gene in cancers according to cBioPortal online TCGA cancer database." (PMID 34917618, 2021). "Further increase in SRSF6 may cause some toxic effects in cancer cells." (PMID 34917618, 2021). "SRSF6 may regulate cancer-associated immunosuppression via these genes." (PMID 34917618, 2021). "In general, SRSF6 overexpression may be positively associated with cancers." (PMID 34917618, 2021). "To characterize the role of SRSF6 in tumor progression, we first analyzed the transcriptional level of SRSF6 in normal and tumor tissues from The Cancer Genome Atlas (TCGA) database." (PMID 40712780, 2025). "Nevertheless, the reasons for the elevated level of SRSF6 in cancer tissues and its role in ferroptosis are still unclear." (PMID 40712780, 2025). "A significant positive correlation was observed between the transcriptional levels of FTO and SRSF6 across multiple cancer types (including tumor and normal tissues) from the TCGA database." (PMID 40712780, 2025). "Accumulated evidence has shown that SRSF6 is a potential oncogenic gene that promotes oncogenic splicing in many kinds of cancers." (PMID 38579171, 2024). "In particular, several splicing factors, such as hnRNP A2/B1, SRSF1, and SRSF6, have been shown to act as driver oncogenes in some cancers; thus, they have gained attention as promising targets for cancer therapy." (PMID 38110955, 2023). "Curently, targeting SRSF6 in cancer is studies using multiple strategies, such as small molecules inhibitors, siRNAs, decoy RNAs or antisense oligonucleotides." (PMID 37904233, 2023). "Our finding that loss of SRSF6 expression impacts homeostatic levels of IFN-β and ISGs motivates future studies of SRSF6-dependent immune dysregulation in cancer, particularly in cancers of myeloid cells." (PMID 36409059, 2022). "Transcriptome analysis also showed that overexpression of SRSF6 in cancer cells induced large-scale changes in transcriptional expression levels and alternative splicing." (PMID 35711821, 2022). "This study revealed that SRSF6 exerted an important role in wound healing process, as well as in cancer when continuously overexpressed." (PMID 34917618, 2021). "SRSF6 promotes cancer cell proliferation via several molecular mechanisms, including repressing apoptosis, modifying energy metabolisms, and activating oncogenic signal transduction." (PMID 34917618, 2021). "Serine/arginine-rich splicing factor 6 (SRSF6) is an important splicing factor that regulates the alternative splicing of hundreds of target genes, including many cancer-associated genes." (PMID 34917618, 2021). "So far, only a few studies reported the relationship between SRSF6 expression and cancer patient prognosis." (PMID 34917618, 2021).
cancer (continued). "The roles of SRSF6 in cancer immunosuppression should be explored because emerging evidences have revealed the important roles of alternative splicing in cancer immunotherapy." (PMID 34917618, 2021). "First, only a few studies analyzed the relationship between SRSF6 expression and disease progress and prognosis of cancer." (PMID 34917618, 2021). "The potential roles of SRSF6 in cancers have also attracted increasing attentions in the past decade." (PMID 34917618, 2021). "In this review, we attempted to summarize the current understanding toward the expression, functions and regulatory mechanisms of SRSF6 during tumorigenesis, and discuss the potential application of targeting SRSF6 in cancer treatment." (PMID 34917618, 2021). "Recent study considers SRSF6 as an oncogene in tumour progression and is frequently overexpressed in cancers." (PMID 31729134, 2020). "Extranuclear distributions of HNRNPA1 and SRSF6 (cytosol/microsome) differed from those of other SRSFs (membrane/organelle) in both cancers." (PMID 27282379, 2016). "In an analysis of the six SF mRNAs, all mRNAs presented unacceptable detection accuracies (≤70 %) in both cancers, and all mRNAs except SRSF6 were disproportionate to the corresponding protein levels in GC." (PMID 27282379, 2016). "HNRNPA1 and SRSF6 in both cancers frequently (≥50 %) showed different distribution patterns from those of the other SFs." (PMID 27282379, 2016). "SRSF6 mRNA level was significantly elevated in tumor tissues in various cancers including HNSC." (PMID 40712780, 2025). "In addition, three other proteins analyzed in this study, HNRNPH1, TRA2A, and SRSF6, were found to be involved in cancer development in previous studies." (PMID 39023715, 2024). "A study analyzed the expression of serine and arginine rich splicing factor 6 (SRSF6) in 311 CRC samples from The Cancer Genome Atlas and Gene Expression Omnibus (GEO) database, and demonstrated that SRSF6-regulates alternative splicing to promote CRC metastasis." (PMID 38087342, 2023). "Notably, we found SRSF1, HECW2, SRSF6, UBE2Z and PCF11, to be linked to carcinogenesis and cancer management 51-62 and are associated with poor prognosis in HMs." (PMID 35711821, 2022). "Upregulation of SRSF6 enhances metastasis and proliferation of cancer cells in vitro and in vivo." (PMID 35984577, 2022). "SRSF5 and SRSF6 play important roles in the development and progression of cancers." (PMID 36289466, 2022). "So far, little is known about the function of SRSF6 in cancer immunosuppression." (PMID 34917618, 2021). "Recently, SRSF6 was also reported to be overexpressed in some cancers." (PMID 34917618, 2021). "Normal skin may only upregulate SRSF6 expression for several days after injury in contrast to the continuous SRSF6 overexpression in cancer." (PMID 34917618, 2021). "This phenomenon may be due to the higher expression levels of SRSF6 in cancer cells than in normal cells." (PMID 34917618, 2021). "Most studies demonstrated that SRSF6 was overexpressed in cancer tissues." (PMID 34917618, 2021). "The potential roles of SRSF6 in cancers have attracted increasing attentions in the past decade." (PMID 34917618, 2021). "Therefore, to understand the value of SRSF6 expression in cancer diagnosis and prognosis, more studies are required to investigate the expression and clinical significance of SRSF6 in cancers." (PMID 34917618, 2021). "Unsurprisingly, SRSF6 shows some anti-tumor effects, which may be overwhelmed by its oncogenic effects in most cancer cells." (PMID 34917618, 2021). "In this review, we describe the gene, mRNA, and protein structure of SRSF6; summarize the current understanding of the expression, functions, and regulatory mechanisms of SRSF6 during tumorigenesis; and discuss the potential application of targeting SRSF6 in cancer treatment." (PMID 34917618, 2021).
cancer (continued). "Moreover, the differential splicing profiles of the SRSF6 gene in distinct CRC cell lines derived from adenocarcinomas or carcinomas also suggested its potential application as a classification marker of CRC patients." (PMID 28276498, 2017). "Thus, targeting the upstream SRSF6/FTO feedback loop might be an alternative strategy to overcome cellular ferroptosis resistance in cancer therapy." (PMID 40712780, 2025). "SRSF6 is an oncogene that may be overexpressed in most cancers." (PMID 39726754, 2024). "Other splicing factors may function against SRSF6 to suppress VEGF165b expression in cancers." (PMID 34917618, 2021). "Therefore, SRSF6 is an oncogene and promising target for cancer therapy." (PMID 34917618, 2021). "The diagnosis and prognosis value of SRSF6 in cancers remain largely unknown." (PMID 34917618, 2021). "Second, the functions of SRSF6 in cancer immunosuppression is unknown." (PMID 34917618, 2021). "When HNRNPA1 and SRSF6 were upregulated in whole cancer-cell lysates, they were predominantly distributed in nuclear and/or cytosol/microsome fractions; the upregulated SFs in the cytosol/microsome fraction were detectable in >50 % of upregulated cases in both cancers." (PMID 27282379, 2016). "Connections between SRSF6 and alternative splicing of the cell death protein BAX complement multiple studies that correlate altered SRSF6 expression levels with cancer progression." (PMID 36409059, 2022). "Cancer cells prefer to impair autoregulatory mechanism and produce transcripts without exon 3 and then increase SRSF6 protein level." (PMID 34917618, 2021).
tumor (25 papers, 2010 to 2025). "Moreover, SRSF6 plays important roles in most of key aspects of tumorigenesis by controlling the alternative splicing of the key tumor-associated genes and can transform cells when overexpressed." (PMID 34917618, 2021). "SRSF6 plays an important role in various stages of tumour development and progression by controlling the splicing of oncogenes and tumour suppressor genes." (PMID 39799463, 2025). "SRSF6 is a proto-oncogene that, when overexpressed, leads to an increase in tumor-promoting isoforms." (PMID 39845971, 2024). "By taking the advantages of the GTEX and TCGA databases, in which RNA-seq results of normal and tumor tissues are displayed independently, we observed that the RNA levels of SRSF6 and Fas were correlated with each other in normal tissue." (PMID 35454897, 2022). "In tumors, these regulations of SRSF6 on Fas were impaired by tumor-specific pathways that need to be defined with further experiments." (PMID 35454897, 2022). "SRSF6 (formerly SRp55) is upregulated in a subset of tumors and is critical for tumor growth, initiation, and maintenance." (PMID 32967226, 2020). "Our study further revealed the effect of SRSF6 on the resistance of tumor cells to ferroptosis." (PMID 40712780, 2025). "Therefore, our work highlighted the crucial roles of the SRSF6/FTO feedback loop in tumor cell ferroptosis resistance and tumor progression, which provided potential therapeutic targets for antitumor treatment." (PMID 40712780, 2025). "As low expressions of SRSF6 can lead to the Fas gene skipping exon 6, this might promote impaired apoptosis in tumor samples." (PMID 35454897, 2022). "Furthermore, the analysis of the RNA-seq data for normal and tumor tissues indicated that the SRSF6 expression level was closely correlated to Fas expression levels in normal tissues, but interrupted in tumors." (PMID 35454897, 2022). "SRSF6 expression is also regulated by a list of key tumor-related genes." (PMID 34917618, 2021). "Therefore, we speculate that such regulatory roles of SRSF6 in apoptosis and immune activation could be disrupted in tumors, thereby promoting the uncontrolled proliferation of tumor cells." (PMID 35454897, 2022). "However, SRSF6 can also induce some tumor suppressive alternative splicing events." (PMID 34917618, 2021). "Therefore, in terms of angiogenesis, increased SRSF6 may inhibit angiogenesis and have an adverse effect on tumor development." (PMID 34917618, 2021). "As expected, the SRSFs with CNV amplification displayed significantly higher expression in tumor tissues compared to normal ones (e.g., SRSF1, SRSF2, SRSF3, and SRSF6)." (PMID 38015716, 2023). "A mouse xenograft model was employed to assess tumor growth upon ZNF561-AS1 knockdown and SRSF6 rescue." (PMID 33622363, 2021). "SRSF6 has been shown to regulate the splicing of one oncogene (INSR) and tumor suppressor genes (DLG1 and MKNK2), modulating their oncogenic and tumor-suppressive isoforms." (PMID 32967226, 2020). "We observed DHX9 and MATR3 (in Tumor A, set 1), HNRNPC and LARP1 (in Tumor A, set 2), SRSF1 (in Tumor B, set 1 & Tumor B, set 2), SRSF6 and IGF2BP2 (Tumor B, set 2), HNRNPU (in Tumor B, set 2 & Tumor C, set 2), and FAM120A and HNRNPA2B1 (in Tumor C, set 2)." (PMID 31892958, 2020). "Moreover, in vivo experiments demonstrated that SRSF6 overexpression reversed the enhanced drug sensitivity observed in NSUN2-knockout cells, leading to tumor growth and final tumor weights comparable to those of NSUN2-knockout controls." (PMID 40083919, 2025). "Corresponding with SRSF6, FTO was also found to be overexpressed in tumor tissues in HNSC." (PMID 40712780, 2025).
infection (4 papers, 2021 to 2025). The state of being infected such as from the introduction of a foreign agent such as serum, vaccine, antigenic substance or organism. "Knockdown of specific SR proteins, including SRSF4, SRSF5, and SRSF6, significantly reduced viral growth, highlighting their critical role in the infection process." (PMID 40522993, 2025). "To further appreciate how macrophages regulate SRSF6 activity, we measured Srsf6 transcript levels during infection and in response to immune agonists." (PMID 36409059, 2022). "Last, we set out to investigate whether SRSF6 plays a more direct role in dictating the outcome of infection with an intracellular pathogen like Mtb." (PMID 36409059, 2022). "We consistently detected an approximately 2-fold decrease in Srsf6 transcript abundance at various time points following M. tuberculosis infection of macrophages, as well as in the lung homogenates collected from Mtb-infected mice (day 21 and 77 post-infection)." (PMID 36409059, 2022). "(P) VSV replication in Srsf6 KD RAW MΦ at 0, 2, 4, 8 hr post infection (MOI = 1) measured by RT-qPCR of Vsvm." (PMID 36409059, 2022). "Interestingly, infection-induced phospho-SR proteins, particularly SRSF4, SRSF5 and SRSF6, were notably enriched in the Golgi apparatuses and large protein complex fractions at 4 hpi, with virus-induced phosphorylation diminished by 8 hpi (EV-A71)." (PMID 40522993, 2025).
SRSF6 also shares sentences with these, for which no sentence is quoted: colon adenocarcinoma (2 papers); acute myeloid leukemia (1); adenocarcinoma (1); alcoholic liver diseases (1); anal carcinoma (1); bacterial infection (1); colorectal tumors (1); diabetic macular edema (1); fronto-temporal dementia (1); Hepatic steatosis (1); HIV-1 infection (1); liver disease (1); lung adenocarcinoma (1); lung squamous cell carcinoma (1); neurodegenerative disease (1); neurological disorders (1); Obesity (1); oral squamous cell carcinoma (1); ovarian tumor (1); pituitary tumor (1); pneumonia (1); PRLomas (1); prostate adenocarcinoma (1); rectal cancer (1); rectum adenocarcinoma (1); Sepsis (1); stomach adenocarcinoma (1); tuberculous pleuritis (1); virus infection (1).